STAT3 (signal transducer and activator of transcription 3)
Diseases named in the same sentence as STAT3 in open-access papers (continued):
Sharing a sentence is not in itself a finding about the gene and the disease.
gastric cancer (continued). "In terms of signaling pathways in gastric cancer cells, iron ions are involved in the regulation of AKT/mTOR, ERK, NF-κB, STAT3, Wnt, and other pathways, indicating their significant impact on the occurrence and progression of gastric cancer through activation or inhibition of these pathways." (PMID 38370477, 2024). "In gastric cancer, STAT3 directly bound to the promoters of negative ferroptosis regulators (GPX4, SLC7A11, and FTH1) and modulated their expression." (PMID 38341410, 2024). "Moreover, CALM2 has been found to stimulate proliferation, migration, invasion, and angiogenesis of HUVECs, as well as M2 polarization of THP1 cells, through the JAK2/STAT3/HIF-1/VEGFA signaling pathway, thereby facilitating gastric cancer metastasis." (PMID 39695099, 2024). "Similarly, in gastric cancer, activation of the CXCL12/CXCR4 axis via the STAT3 pathway induces downregulation of E-Cadherin and upregulation of N-Cadherin, Vimentin, and Snail, enhancing EMT, migration, and the invasiveness of gastric cancer cells." (PMID 38920657, 2024). "An increase in the expression of RIPK2 facilitates resistance to innate and adaptive immune therapeutic techniques via pathways such as the IL-6/JAK/STAT3 signaling pathway, the interferon-γ response, and the interferon-α response; thus, RIPK2 plays an important role in gastric cancer." (PMID 39309860, 2024). "Additionally, Toosendanin, an extract from Chuanlianzi, downregulates STAT3 expression, inhibiting HIF-1α activity and thus attenuating AEG in gastric cancer cells." (PMID 39906672, 2024). "Furthermore, our analysis extended to STAT3 and phosphorylated STAT3, recognized targets of XYA-2 in its anti-gastric cancer activity." (PMID 38250721, 2024). "Additionally, a strong positive correlation between STAT3/pSTAT3(Tyr705) levels and COX-2 expression has been identified in gastritis and gastric cancer tissues." (PMID 38883131, 2024). "In gastric cancer cells, SHMT2 modulates the stability of HIF1α, thus controlling a network of hypoxia-responsive genes that have regulatory effects on complementary pathways, including VEGF and STAT3." (PMID 39309860, 2024). "In turn, STAT3 can directly bind to the LINC00501 promoter and activate the expression of LINC00501, thereby forming a positive feedback loop and accelerating the growth, invasion, and metastasis of gastric cancer cells." (PMID 39309860, 2024). "However, a gastric cancer study identified connections between mTOR/PKM2 and STAT3/c‐Myc signaling pathways, constituting a molecular network that jointly regulates the energy metabolism in gastric cancer." (PMID 39584783, 2024). "For example, inhibition of STAT3 could regulate GPX4, SLC7A11 and FTHI to induce ferroptosis, which can restore the sensitivity of gastric cancer cells to chemotherapy drugs." (PMID 38347435, 2024). "Recent studies involving single-cell RNA sequencing of gastric cancer and adjacent tissues found that Tregs were recruited to gastric cancer tissues and have further demonstrated that Tregs promote the stemness of gastric cancer cells through the IL13/STAT3 pathway." (PMID 39605357, 2024). "Collectively, our analysis of transcriptomics data from human gastric cancer patients and data from our in vivo gastric cancer model demonstrate the concomitant elevation of YAP1 and receptor components of the gp130/STAT3 signalling pathway during gastric cancer development." (PMID 37957015, 2024). "Furthermore, we identified STAT3 as a downstream ROR1 target in OC cells, which is in line with previous findings in ROR1+ leukemic cells and gastric cancer." (PMID 37400436, 2023). "In gastric cancer tissues, the expression of HK2 and PFK is decreased when STAT3 is knocked down." (PMID 37599427, 2023). "Finally, miR-625-5p/NFIX, miR-124-3p/EZH2, miR-625-5p/STAT3 and miR-29b/KDM2A are other molecular axes regulated by LINC00511 in gastric cancer." (PMID 37124625, 2023).
gastric cancer (continued). "Hydrogen sulfide inhibits MGAT5 and displays antitumor efficacy in gastric cancer MMP13 has been shown to be upregulated in gastric cancer and can be inhibited by SIRT1 which modulates the STAT3/MMP13 axis to suppress cell proliferation and metastasis in gastric cancer." (PMID 37256183, 2023). "It is a constitutively active signaling pathway in gastric cancer, its expression was investigated in HGC-27 cell, and it was observed that the knockdown of TMEM45B significantly decreased phosphorylation and activation of the JAK2 and STAT3 proteins." (PMID 37936608, 2023). "Silbinin extracted from milk thistle is a known flavonolignan compound, and in the gastric cancer cell line (MGC-803), it negatively influenced the STAT3 pathway to activate caspase 3 and caspase 9 activities to induce apoptosis with a negative impact on survival, Cyclin B1, and CDK1." (PMID 36769170, 2023). "The correlation results of STAT3 and miR-4500 expression in gastric cancer tissues and paired normal tissues showed negative coexpression of STAT3 and miR-4500." (PMID 36246567, 2022). "In gastric cancer, CXCR7 was found to promote cancer progression through the STAT3/c-Myc pathway." (PMID 35264069, 2022). "In human gastric cancer, GM-CSF expressed by tumors induces the activation of neutrophils and triggers the expression of PD-L1 through activation of the Janus kinase (JAK)-signal transducer and activator of transcription 3 (STAT3) signaling pathways." (PMID 36514901, 2022). "This disagreement may be due to forced GSDMD overexpression, which can reverse gastric cancer cell proliferation by inactivating the ERK, STAT3, and PI3K/AKT pathways, and then inhibiting the Cyclin A2/CDK-2 complex to arrest the S/G2 phase transition." (PMID 36120543, 2022). "The JAK/STAT3 and PI3K/AKT signaling pathways could be considered potential targets for combating CAF-induced chemotherapy resistance in gastric cancer." (PMID 36032075, 2022). "Our data suggested that SDL-1 as a potent STAT3 degrader may be a potential anti-gastric cancer drug candidate, and PROTAC targeting STAT3 may be a new and effective gastric cancer therapeutic strategy." (PMID 36034876, 2022). "Accordingly, we further examined whether the effects of STAT3 depletion was in accordance with the effects of lncRNA RPSAP52 depletion and miR-665 mimics in gastric cancer cells." (PMID 35322746, 2022). "FFAs-activated p-STAT3/miR-193a-3p/LAMC1 axis played an important feedback regulation role in the reciprocal interaction between gastric cancer cells and preadipocytes which directly contributed to gastric cancer peritoneal metastasis." (PMID 35541892, 2022). "Previous reports indicated that the upregulation of STAT3/HK2 contributed to the activation of dendritic cells by leptin-induced glycolytic metabolism, and circular RNA circCUL3 eliciting the Warburg effect of gastric cancer." (PMID 36431990, 2022). "Taken together, the effects of STAT3 depletion on cell proliferation, apoptosis and cell cycle are consistent with LncRNA RPSAP52 depletion and mir-665 overexpression in gastric cancer cells, suggesting that STAT3 is downstream target of the LncRNA RPSAP52/mir-665 axis target gene." (PMID 35322746, 2022). "Similarly, the application of OPB-31121 (oral STAT3 inhibitor) repressed constitutive and IL-6-induced JAK/STAT3 signalling in gastric cancer lines." (PMID 36429126, 2022). "In gastric cancer, Zhao and colleagues indicated that IL6 could promote proliferation, invasion, and lymphangiogenesis by regulating the JAK/STAT3/VEGF-C signaling." (PMID 36276992, 2022). "Moreover, MIA-602 was found to inhibit the growth of gastric cancer in vitro and in vivo by blocking p21-activated kinase 1 (PAK1), STAT3 and NF-kB inflammatory pathways." (PMID 36232554, 2022). "Further analysis found that at mRNA Level, STAT3 was highly expressed in malignant gastric cancer cells compared with normal and adjacent non-tumorous samples in TCGA and GTEx cohort." (PMID 36034876, 2022).
gastric cancer (continued). "Human HGC-27 gastric cancer cells were transfected with siRNA target to STAT3 (si-1, si-2) and si-NC (negative control)." (PMID 34544479, 2021). "For example, in gastric cancer cells, PPIs have been shown to inhibit the expression and nuclear translocation of hypoxia-inducible factor 1 α (HIF-1α), Wnt/β-catenin signaling, and the IL-6/STAT3 signaling pathway." (PMID 34262645, 2021). "The use of ITGA2 blocking antibodies inhibits migration and induces apoptosis of gastric cancer cells, while overexpression of ITGA2 stimulates PD-L1 expression by activating the STAT3 signaling cascade, leading to the more aggressive behavior of malignant pancreatic cells." (PMID 34503200, 2021). "By integrated experimental and bioinformatic analyses, we have previously demonstrated that depletion of STAT3 resulted in hypomethylation of STAT3 targets and tumor suppressors, NR4A3, and SPG20, in a gastric cancer cell line with constitutive activation of JAK/STAT signaling." (PMID 33886682, 2021). "For AKT/STAT3 signaling, it participated in NFIB-mediated EMT of gastric cancer." (PMID 33390776, 2021). "Thus, the data indicates that ABZ can modulate the activation of STAT3 and STAT5 by pleiotropic mechanisms in gastric cancer cells." (PMID 33807326, 2021). "Importantly, gastric cancer-driven GM-CSF induces high PD-L1 expression in tumor-infiltrating neutrophils and TAMs via JAK/STAT3 and IL-8 signaling, respectively." (PMID 33406733, 2021). "Indeed, treatment of STAT3 inhibitor, JSI-124, resulted in a downregulation of C11orf87 expression in AGS gastric cancer cells." (PMID 33886682, 2021). "As aberrant phosphorylation of STAT3 and STAT5 proteins can regulate the growth and progression of gastric cancer, we postulated that ABZ may interrupt the activation of these oncogenic transcription factors." (PMID 33807326, 2021). "TQ at 25, 50 and 75 μM inhibited JAK2 and c-Src activity and induced apoptosis by inhibiting the phosphorylation of STAT3 and STAT3 downstream genes, such as Bcl-2, cyclin D, survivin, and VEGF, and upregulating caspases-3, caspases-7, and caspases-9 in gastric cancer cell lines HGC27 and BGC823." (PMID 33923474, 2021). "Overall, ABZ can serve as an efficient blocker of both STAT3 and STAT5 proteins by promoting oxidative stress as well as inducing expression of SHP-1 and thus exhibit its multifaceted actions against gastric cancer cells, which need to be validated in preclinical studies in future." (PMID 33807326, 2021). "It was demonstrated that histone deacetylases as well as c-Myc, STAT1 and STAT3 may contribute independently to the transcriptional suppression of TMEFF2 in colon cancer, prostate cancer and gastric cancer." (PMID 33663520, 2021). "In this study, it was investigated whether ABZ can impact the activation of STAT3 and STAT5 pathway in gastric cancer cells and thereby exhibit pleiotropic actions on tumor progression as well as survival." (PMID 33807326, 2021). "Moreover, TANs were localized mainly at the invasive margin of human gastric cancer tissues and expressed abundantly IL-17, which enhanced the migration, invasion and EMT of gastric cancer cells, through the activation of JAK2/STAT3 pathways." (PMID 32422991, 2020). "Additionally macrophages are also the major sources of chemokines and chemokine receptors in the gastric cancer microenvironment, such as CXCL1 and CXCL5, and promote migration through activating the CXCR2/STAT3 feed-forward circuit." (PMID 33112406, 2020). "Interestingly, miR-149 has been shown to be involved in tumor progression by regulating the interleukin-6 (IL-6)/signal transducer and activator of transcription 3 (STAT3) pathway in esophageal and gastric cancer." (PMID 32455867, 2020). "Moreover, STAT3 pathway was found highly activated in both NOC-transformed cell subclones and clinical gastric cancer tissues, coordinating with the elevation of H3S10 phosphorylation." (PMID 32041943, 2020).
gastric cancer (continued). "Although the downstream signaling pathways of Ephrin A1-EPHA2 in gastric cancer cells remain unclear, the effects of C1GALT1 and EPHA2 on phosphorylation of these molecules, including EPHA2, STAT3, AKT, ERK, FAK, and Src, were similar." (PMID 32005975, 2020). "Similarly, in case of gastric cancer, theactivation of STAT-3 by human T-cell lymphotropic virus I can transform T cells,involving a direct effects of STAT-3 and epithelial-mesenchymal transition(EMT)." (PMID 32167126, 2020). "In gastric cancer, CAFs also influence carcinogenesis through IL-6 induction in metastasis and invasion through factor overexpression increasing the epithelial-mesenchymal transition (EMT), finally activating the JAK2/STAT3 pathway." (PMID 32499779, 2020). "For instance, TLR2 is overexpressed in more than 50% of human gastric cancers due to the hyperactivation of the STAT3 oncogene that directly induces TLR2 transcription, and increased STAT3 activation and TLR2 expression correlate with poor prognosis in gastric cancer patients." (PMID 33321934, 2020). "Furthermore, STAT3 signaling was reported to be involved in IGF1/IGF1R‐mediated cell growth and metastasis in gastric cancer." (PMID 32851683, 2020). "Prostaglandin D2 (PGD2) synthase (PTGDS) and its receptor PTGDR2 are negatively correlated with stem genes (Sall4 and Lgr5) in gastric cancer, which restricts tumor self-renewal, growth, and metastasis by relying on the PTGDR2 pathway to inhibit STAT3 phosphorylation and nuclear expression." (PMID 33312950, 2020). "IGF1/IGF1R/STAT3 signaling promoted IFITM2 expression and gastric cancer growth and metastasis." (PMID 32851683, 2020). "Taken above, there may exist an interplay between STAT3 and STAT1 regulated by OSM, and the different transformations between them may affect the progress of gastric cancer." (PMID 31871447, 2019). "STAT3 was identified to be a significant inducer of EMT by the transcriptional activation of slug and could also regulate PD-L1expression in gastric cancer, which was analogously demonstrated to our results in A2780cis cells." (PMID 31105696, 2019). "Our current research has identified OLC8 as a novel oncogenic lncRNA in IL‐11/STAT3 signaling, and OLC8 may constitute a potential target for gastric cancer intervention." (PMID 31273847, 2019). "As the IL-6-induced transcriptional stimulation of MMP-9/2 results from the activation of STAT3 via the JAK2/STAT3 pathway in gastric cancer and AGS cells, we tested the STAT3 phosphorylation level in MKN-28 and AGS cells exposed to rIL-6 for different time points." (PMID 31817563, 2019). "Furthermore, As2O3 attenuated STAT-3 activity and epithelial-mesenchymal transition (EMT) through induction of SHP-1 in gastric cancer cells." (PMID 30477221, 2018). "Therefore, we consider that SHP-1 is a key regulator of dephosphorylation of STAT3 and has an anti-EMT effect in gastric cancer cells." (PMID 29409467, 2018). "We investigated the effect of arsenic trioxide (ATO) for inhibition of signal transducer and activator of transcription 3 (STAT3) and epithelial-mesenchymal transition (EMT) in gastric cancer cells, and the role of SH2 domain-containing phosphatase-1 (SHP-1) during this process." (PMID 29409467, 2018). "In gastric cancer, the role of SHP-1 for inhibition of STAT3 has been rarely reported." (PMID 29409467, 2018). "Thus, inhibition of the JAK2/STAT3 signaling pathway is a crucial step for repression of invasion and EMT in gastric cancer." (PMID 29409467, 2018). "Towards this, we used patient tissues representing different stages of gastric cancer including gastric pre-cancerous lesions, early gastric cancer, and advanced gastric cancer, and probed SIRT1, STAT3 and phosphorylated STAT3 (pSTAT3) levels using immunohistochemistry." (PMID 28061480, 2017).
gastric cancer (continued). "In the current study, gastric cancer cells were then treated with rhodium(III) complex 6 (RHD6), a novel STAT3 inhibitor, to determine whether the suppression of STAT3 would derepress GATA6 and TFF1/2." (PMID 27598141, 2016). "Collectively, these data indicate that the antitumorigenic activity of Cu-I was independent of its anti-STAT3 activity in gastric cancer cell lines." (PMID 26890145, 2016). "Our current study, however, is the first to demonstrate that activation of STAT3 could result in promoter hypermethylation and epigenetically silence another target, NR4A3, in gastric cancer." (PMID 27528092, 2016). "Moreover, Yao and colleagues recently demonstrated the existence of cross-talk between STAT3 and NFκB based on the findings that STAT3α siRNA abolishes NFκB binding to fascin-1 and subsequently inhibits metastasis of MKN45 human gastric carcinoma cells." (PMID 27036017, 2016). "More importantly, activated STAT3 binds to and inhibits Stathmin 1, resulting in microtubule stability in non-Hodgkin lymphoma and gastric cancer human cell lines, but Stathmin 1 has never been investigated in MPN." (PMID 26356819, 2015). "Here we show that treatment of human AGS gastric cancer cells with the Janus Kinase (JAK) inhibitor WP1066 dose-, and time-dependently inhibits STAT3 phosphorylation, in conjunction with reduced JAK2 phosphorylation, reduced proliferation and increased apoptosis." (PMID 24804649, 2014). "Combinatorial targeting on both HER2 and STAT3 may enhance the efficacy of trastuzumab or other HER2-targeting agents in HER2-positive breast and gastric cancer." (PMID 25327561, 2014). "Furthermore, the expression of IL-6, survivin, STAT3, STAT3 phosphorylation (p-STAT3), and VEGF were determined in human gastric cancer and adjacent normal mucosa through Western blot and immunohistochemistry." (PMID 24116074, 2013). "In the 24 AFP-negative gastric cancer samples, 8 (33%) primary tumors were positive and 16 (67%) were negative for STAT3 expression." (PMID 23382965, 2013). "In addition, the expression of IL-6, survivin, STAT3, p-STAT3, and VEGF were increased in human gastric cancer tissues as compared to adjacent normal mucosa." (PMID 24116074, 2013). "In addition, inhibition of Stat3 function by DPP, another Stat3 inhibitor, resulted in significant decreases in cisplatin resistance and enhanced apoptosis in drug-resistant gastric cancer cells." (PMID 23382914, 2013). "Moreover, IL-6 and STAT3 downstream signals such as IL-10 and VEGF were reduced in patients after removal of gastric cancer as compared to pre-operation." (PMID 24116074, 2013). "In addition, IL-6/STAT3 signals including surviving and VEGF were significantly augmented in gastric carcinoma tissues as compared to adjacent normal mucosa." (PMID 24116074, 2013). "Deregulated STAT-3 activation has been suggested to play an important role in overexpression of VEGF and increased angiogenic phenotypes in gastric cancer, which may contribute to gastric cancer development and progression." (PMID 22937084, 2012). "Surprisingly, honokiol induced STAT-3 dephosphorylation of Tyr705, but not Ser727, residues in these human gastric cancer cells." (PMID 22937084, 2012). "Since previous research demonstrated that STAT3 is required in KRAS-driven oncogenic transformation, we hypothesized that dual inhibition of PI3K and STAT3 would be effective in KRAS mutant gastric cancer cell lines." (PMID 22159814, 2012). "Although STAT3 is often expressed at a high level and is constitutively activated in many human tumours, the mechanisms of STAT3 activation have not been completely characterised in gastric cancer." (PMID 21730976, 2011). "In conclusion, we have shown that gastric cancer cell lines can be classified on the basis of the mechanism of STAT3 activation (induced by MET or IL-6) into distinct and non-overlapping subsets." (PMID 21730976, 2011).